ABCG2 (ATP binding cassette subfamily G member 2 (JR blood group))
Diseases named in the same sentence as ABCG2 in open-access papers (continued):
Sharing a sentence is not in itself a finding about the gene and the disease.
glioma (continued). "Here, we reported that this pathway participated in TMZ-R glioma, and it could be disrupted by fasudil, leading to the dislocation of ABCG2 via suppression of p-moesin." (PMID 29416017, 2018). "Our data revealed a novel mechanism for ABCG2 regulation in TMZ-R gliomas." (PMID 29416017, 2018). "In our study, we also found that ABCG2 was overexpressed in resistance cells, indicating that ABCG2 may play important roles in TMZ-R gliomas." (PMID 29416017, 2018). "oHA down-regulated ABCG2/BCRP expression in C6/lacZ7 glioma cells." (PMID 30513961, 2018). "Moreover, ABCG2 downregulation inhibits glioma stem cell migration and invasion, where its expression partly dictates the behavior of the side population of high-grade GSCs." (PMID 26981778, 2016). "We recently described the myeloid Elf-1 like factor (MEF) as a novel key transcription factor in promoting glioma stemness and malignancy through direct transcriptional activation of Sox216, one of the genes shown here to be activated by ABCG2 in murine and human glioma cultures." (PMID 27456282, 2016). "Additionally, ABCG2-negative cancer cells are able to form tumors in breast, prostate, colon, and glioma xenograft models at the same rate as ABCG2-positive cancer cells." (PMID 26714461, 2015). "HA-CD44 interactions also regulate expression of ABCG2 (BCRP) in glioma cells." (PMID 24124770, 2013). "A further resistance factor suggested to be relevant in glioma is the efflux transporter ABCG2." (PMID 24380367, 2013). "Several questions need to be answered regarding the role of ABCG2 in glioma biology." (PMID 22685459, 2012). "Furthermore, the inhibition or knockdown of ABCG2 in rodent models can enhance the accumulation of chemotherapeutic drugs in the brain, suggesting a potential strategy to improve drug delivery and efficacy in glioma treatment." (PMID 38542090, 2024). "We asked whether ABCG2 activity itself promoted radiation resistance of PIGPCs or U87 glioma cells." (PMID 27456282, 2016). "The heterogeneity of gliomas and the complexity of the BBB pose significant obstacles to the effective delivery of ABCG2 inhibitors." (PMID 38542090, 2024). "Thus, the ABCG2 profile, which encompasses ABCG2 score, microvascular density, and staining intensity in the tumor’s blood vessels, plays a crucial role in predicting tumor progression and survival in patients with glioma tumors, as well as tumor resistance to chemoradiotherapy." (PMID 38542090, 2024). "In this study we aimed to investigate the role of SeNPs and 0.2% Cs-SeNPs on the expression levels of genes involved in drug resistance in glioma, including MRP1 (ABCC1) and BRCP (ABCG2), which can predict clinical progression." (PMID 35957037, 2022). "The expression levels of ABCG2 are significantly higher in high-grade gliomas (grades III and IV) than in low-grade gliomas (grades I and II)." (PMID 35740330, 2022). "The intraoperatively observable fluorescence effect in gliomas seems thus to be a result of increased PpIX synthesis (PPOX, CPOX) and decreased efflux (ABCG2) outweighing its concurrently increased further metabolization to heme (FECH)." (PMID 35665365, 2022). "Further, the expression of drug-resistance protein ABCG2, autophagy related proteins, and PI3K/Akt/mTOR pathway were measured by western blot or qRT-PCR in TMZ-treated glioma cells." (PMID 34454479, 2021). "All these data supported a focal disruption of the BBTB in high-grade gliomas, which led to enhanced brain distribution of small-molecule drugs, which were subject to ABCB1 and/or ABCG2 efflux transport." (PMID 31832814, 2019). "The results demonstrated that the expression ratios of ABCG2, CXCR4 and nestin were higher on glioma stem cells than on brain glioma cells." (PMID 28615716, 2017). "The expression of ATP-binding cassette subfamily G member 2 (ABCG2), chemokine receptor type 4 (CXCR4) and nestin were identified on human brain glioma cells and glioma stem cells (GSCs)." (PMID 28615716, 2017).
glioma (continued). "We investigated levels of multiple drug resistance-related genes in U87 and primary glioma cells, including genes related to drug efflux (ABCB1, ABCC1, ABCC2, ABCC4, ABCG2, ATM), DNA damage repair (MGMT) and stemness (CD133)." (PMID 27486877, 2016). "Before drug treatments, the expression ratios of drug-resistant ABC transporters in glioma cells (ABCB1 = 0.50 ± 0.06, ABCC1 = 0.26 ± 0.10, and ABCG2 = 0.57 ± 0.01) were evidently lower than those in GSCs (ABCB1, ABCC1 or ABCG2 = 1, respectively)." (PMID 25153726, 2014). "For the ABCG2 and pathological grade of cancer, our data in HCC is concordant with those observed in glioma." (PMID 23153066, 2012). "In a rat RG2 glioma model, tesmilifene reduced transendothelial electrical resistance and inhibited key efflux transporters—P-gp/ABCB1, BCRP/ABCG2, and MRP1—resulting in a 2.7-fold increase in fluorescein accumulation and enhanced albumin permeability within tumor tissue." (PMID 40806198, 2025). "The ATP-binding cassette sub-family G member 2 (ABCG2), also known as breast cancer resistance protein (BCRP), has emerged as a pivotal player in the multidrug resistance phenomenon observed in cancer treatment, including glioma treatment." (PMID 38542090, 2024). "Due to its potential to penetrate the BBB without restriction by the ABCB1 and ABCG2 efflux transporters, the anti-glioma effects of this drug have been investigated." (PMID 36839989, 2023). "For this purpose, we compared the mRNA as well as protein expression of CPOX, PPOX, FECH, and ABCG2 in 19 glioma tissue samples with presence of strong 5-ALA induced fluorescence during surgery to 21 non-fluorescing glioma samples." (PMID 35665365, 2022). "ABCG2 could determine the response of glioblastoma to TMZ, and its inhibition increases sensitivity to TMZ and suppresses the growth of TMZ-resistant glioma." (PMID 34454479, 2021). "ABCB1/P-gp, ABCG2/BCRP, ABCC1/MRP1, ABCC4/MRP4, and ABCC5/MRP5 up-regulation has been observed in glioma cells at the mRNA and/or protein level; moreover, MRP3 de novo protein expression has also been detected in high grade gliomas (detailed below)." (PMID 31878061, 2019). "ABCG2 (ATP-binding cassette transporter subfamily G member 2), also called BCRP (breast cancer resistance protein), regulates self-renewal and stem cell marker expression but not tumorigenicity or radiation resistance of glioma cells." (PMID 29535786, 2018). "Therefore, nestin, ABCG2 and CXCR4 are included as the phenotype markers for identifying glioma stem cells." (PMID 28615716, 2017). "Neither ABCB1 nor ABCG2 expression was detected in the brain parenchyma under normal conditions, specifically astrocytes and glial cells, which are cells of origin for some gliomas." (PMID 29186899, 2017). "Despite these findings, some studies showed that ABCG2 knockdown does not affect TMZ sensitivity in glioma cell lines." (PMID 29186899, 2017). "Downregulation of ABCG2 expression decreases the chemoresistance of glioblastoma cancer stem cells, and ABCC3 and ABCC5 have been reported to be expressed higher than the other ABCC subfamily members in glioma." (PMID 25605243, 2015). "Moreover, glioma cell populations sorted for the expression of the ABCG2-transporter, revealed that both ABCG2+ and ABCG2− populations exhibited similar tumorigenicity." (PMID 20414333, 2010). "The presence of ABCG2 alone does not indicate that glioma cells are resistant to PDT." (PMID 39201395, 2024). "Interestingly, immunostaining of ABCG2 showed that 100% of the CD133-positive glioma stem cells were ABCG2-positive, whereas no CD133-negative fraction expressed ABCG2." (PMID 35740330, 2022). "Transcriptomic analyses showed an increased expression of ABCG2, ALDH1, FGF1 stem cell markers in the pale region, when compared to the tumor mass, suggesting the presence, in the infiltrating front of the tumor, of a glioma stem cell (GSC) population possibly responsible for tumor recurrence." (PMID 33066172, 2020).
glioma (continued). "Interestingly, the accumulation of PpIX in glioma stem cells was not enhanced by ABCG2 inhibition using reserpine, but was enhanced by deferoxamine-mediated iron chelation, suggesting that PpIX accumulation depends on several factors." (PMID 31083682, 2019). "Therefore, potential mechanistic explanations for the TMZ chemosensitivity of miR-433-3p in glioma may be due to apoptosis activation, cell cycle distribution and downregulation of CREB and ABCG2." (PMID 27926502, 2017). "Moreover, PTEN was described as regulating the SP but not the expression of ABCG2 in glioma tumor stem-like cells through the PI3K/Akt pathway." (PMID 24603487, 2014). "Moreover, the SHH pathway is thought to be activated in primary GBM and glioma cell lines, leading to the overexpression of some drug efflux molecules (e.g., ABCB1, ABCG2 [BCRP], and ABCC1 [MRP1]), and MGMT and BMI1, which may explain its association with therapy-resistance." (PMID 32722427, 2020). "In contrast to ABCG2, ABCB1 protein amounts in 60 CNS tumor samples, including several gliomas, revealed no significant change in expression compared to the normal brain parenchyma." (PMID 29186899, 2017). "In addition, treatment with nicardipine, an ABCG2 competitive inhibitor, sensitized CD133-positive glioma stem cells to mitoxantrone, whereas no synergistic effect was observed in CD133-negative tumor cells." (PMID 35740330, 2022).
glioblastoma (62 papers, 2008 to 2025). The most malignant astrocytic tumor (WHO grade IV). "ABCG2, a well-known gene associated with multidrug resistance, is notably upregulated in glioblastoma, a highly aggressive type of cancer." (PMID 39931465, 2025). "ABCG2 encodes an ATP-binding cassette transporter that functions as an efflux pump and is associated with chemoresistance in glioblastoma cell lines." (PMID 35456993, 2022). "OCT3/4 has been confirmed to be involved in the chemotherapy resistance of glioblastoma cell lines by affecting the expression of the drug efflux pump gene ABCG2, which encodes breast cancer resistance protein (BCRP)." (PMID 34199840, 2021). "In a study of 50 human glioblastoma patients high ABCG2 levels were associated with much worse survival with an adjusted hazard ratio of 2.35." (PMID 29186899, 2017). "We took advantage of the publicly available databases to evaluate whether ABCB1 and ABCG2 genes were altered, by mutation or amplification, in CNS tumors, glioblastoma and medulloblastoma (the most common pediatric CNS tumor- will be described in details later)." (PMID 29186899, 2017). "According to the Ivy Glioblastoma Atlas project, we found that HIF1α, HIF2α, and ABCG2 expression was greater in the microvascular proliferation region (CTmvp) than in the leading-edge region (LE)." (PMID 40370575, 2025). "In their study, the scientists explored the role of ABCG2 in regulating Ce6 accumulation and phototoxicity, employing two glioblastoma cell lines: U251-V and U251-EV." (PMID 39337463, 2024). "Several studies have observed membranous and nuclear expression of ABCG2 in malignant tumor cells, such as lung and laryngeal carcinomas and glioblastoma multiforme." (PMID 36982894, 2023). "In vitro, siRNA reduce ABCB1/ABCG2 mRNA and ABCB1/ABCG2 protein expression in drug-resistant cancer cells such as U87 glioblastoma cells or hepatocellular carcinoma cells." (PMID 36973040, 2023). "Glioblastoma cells with high ABCG2 expression accumulate less photosensitizers and require higher doses of light for elimination." (PMID 37759900, 2023). "Elevated levels of ABCG2 in doxycycline-induced sU251MG-V glioblastoma cells led to a reduced accumulation of PpIX, and higher doses of light were required to reduce cell viability." (PMID 37759900, 2023). "The transcriptomic analysis also revealed that GZ17-6.02 treatment results in suppression of several genes implicated in glioblastoma growth and invasion, such as EGR1, ASCL1, CD109, ABCG2, and CDH5." (PMID 35456993, 2022). "It has been demonstrated that miR-328 targets and inhibits ABCG2 in glioblastoma cells, thereby sensitizing the cells to chemotherapeutics." (PMID 35804989, 2022). "It has been demonstrated that miR-381 overexpression effectively sensitized glioblastoma U251 cells to temozolomide by targeting various ABC transporters including ABCG2, ABCC3, and ABCC5." (PMID 35804989, 2022). "miR-328 inhibits the expression of ABCG2 and sensitizes glioblastoma cells to the anticancer drugs (including mitoxantrone and doxorubicin)." (PMID 34434499, 2021). "Very robust ABCG2 expression was detected in anaplastic astrocytoma and glioblastoma patient samples by Western blot and modest level in grade II astrocytoma." (PMID 29186899, 2017). "In certain glioblastomas, high expression of ABCB1 and ABCG2 has been reported to associate with poor prognosis." (PMID 29186899, 2017). "ABCG2 protein has been detected in both mouse models of glioblastoma and human glioblastoma samples by IHC (Immunohistochemistry)." (PMID 29186899, 2017). "Expression of miR-9, in U87 and T98G glioblastoma cell lines, was associated with increased amounts of ABCB1 and ABCG2 mRNA and protein." (PMID 29186899, 2017). "The effects of Akt were thought to be mediated by the activation of the Wnt/β-catenin pathway and GSK3β phosphorylation in mammary stem/progenitor cells, and by Akt-induced ABCG2 activation in glioblastoma stem-like cells." (PMID 25625591, 2015).
glioblastoma (continued). "In this study, we found that CD133+ and ABCG2+ cells were sparsely distributed throughout both the G1 and G2 glioblastoma tissues." (PMID 26563263, 2015). "We therefore investigated promoter methylation of ABCB1 and ABCG2 in 64 glioblastoma patients using the pyrosequencing technology, which allows unequivocal quantification of the methylation status, and used MGMT promoter methylation as positive control." (PMID 24380367, 2013). "Our data argue against any relevant impact of MGMT, ABCB1 or ABCG2 promoter methylation on overall survival of glioblastoma patients." (PMID 24380367, 2013). "In summary, our study represents a combined investigation of promoter methylation and gene polymorphisms of the pivotal drug resistance genes MGMT, ABCB1 and ABCG2 in glioblastoma multiforme." (PMID 24380367, 2013). "PPARγ also regulates ABCB1 and ABCG2 in human glioblastoma cell lines in vitro." (PMID 36973040, 2023). "Moreover, co-localization of both P-gp and ABCG2 proteins is observed in glioblastoma cells, which is correlated to their joint functioning as drug transporters." (PMID 35804989, 2022). "Analysis of overall survival (OS) demonstrates that a low expression level of ABCG2 was linked to poor prognosis for the cancer types of adrenocortical carcinoma (ACC) (p = 0.030), glioblastoma multiforme (GBM) (p = 0.048), and KIRC (p < 0.001) within the TCGA project." (PMID 36555598, 2022). "Expression of ABCG2 appears related to survival in glioblastoma patients." (PMID 29186899, 2017). "Furthermore, treating the patient-derived glioblastoma tumor spheres with an ABCG2 inhibitor reduced self-renewal of these cells suggesting that ABCG2 is important for maintaining their stemness." (PMID 29186899, 2017). "Thus, we focused on establishing new pyrosequencing assays for the analysis of the methylation status of the ABCB1 and the ABCG2 promoter in a collective of 64 glioblastoma patients using MGMT promoter methylation as reference." (PMID 24380367, 2013). "In the SPs of both mouse and human glioblastomas (that are enriched in CSCs), Akt inhibition by the synthetic alkylphosphocholine, perifosine, lowered ABCG2 expression on the plasma membrane and decreased efflux of mitoxantrone, another ABCG2 substrate." (PMID 24281174, 2010). "While with the high expression of the ABCG2 transporter protein (CD338), the accumulation of PPIX in MB appears to be lower than that in glioblastoma (GBM)." (PMID 39518115, 2024). "Transfecting U87 glioblastoma cells with synthetic miR-145 decreases both ABCB1 and ABCG2 protein levels, which in return increases sunitinib cytotoxicity." (PMID 36973040, 2023). "In addition, inhibition of ABCG2 efflux in other tissues might improve drug pharmacokinetics, which could be especially relevant for orally administered drugs or drugs that need to cross the blood–brain barrier, for example to treat glioblastomas." (PMID 37147730, 2023). "iPSC induced with U87MG CSCs CM were found to overexpress CSC-specific markers CD133, CD44, ABCG2 and ABCC2, which confirmed these cells as iPSC-derived glioblastoma stem cells (iPSC-GSCs); these markers are more than monolayer U87MG, as observed." (PMID 37509281, 2023). "For example, a lower expression level of ABCG2 was detrimental to the survival of adrenocortical carcinoma (TCGA-ACC), glioblastoma multiforme (GBM), and kidney renal clear cell carcinoma (KIRC) patients." (PMID 36555598, 2022). "The in vitro expression of ABCG2, at the transcription and at post-translational level, was significantly decreased in isogenic U87MG human glioblastoma cell lines by PD153035 (an EGFR antagonist)." (PMID 30181510, 2018). "The alkylating agent TMZ is the drug of choice in treating glioblastoma and the contribution of ABCB1 and ABCG2 to its efficacy has been widely studied." (PMID 29186899, 2017). "In glioblastoma cell lines, TMZ treatment increases the side population (SP), a phenotype characterized by high ABCG2 function and an enrichment of stem cells." (PMID 29186899, 2017).